DHX9P1 (DEAH-box helicase 9 pseudogene 1)
Synonyms: formerly DDX9P; DHX9P
Gene: Processed pseudogene on chromosome 13 (76,984,868 to 76,987,943, forward strand). Ensembl gene ENSG00000228002.
Diseases named in the same sentence as DHX9P1 in open-access papers:
DHX9P1 is named in the same sentence as 1 disease in open-access papers, as found by Europe PMC text mining. Sharing a sentence is not in itself a finding about the gene and the disease.
DHX9P1 shares sentences with these, for which no sentence is quoted: Alzheimer disease (1 paper).